TCF7L2 (transcription factor 7 like 2)
Description:
Participates in the Wnt signaling pathway and modulates MYC expression by binding to its promoter in a sequence-specific manner. Acts as a repressor in the absence of CTNNB1, and as activator in its presence. Activates transcription from promoters with several copies of the Tcf motif 5'-CCTTTGATC-3' in the presence of CTNNB1. TLE1, TLE2, TLE3 and TLE4 repress transactivation mediated by TCF7L2/TCF4 and CTNNB1. Expression of dominant-negative mutants results in cell-cycle arrest in G1. Necessary for the maintenance of the epithelial stem-cell compartment of the small intestine.
Synonyms: TCF-4; TCF4
Tractability: Small molecule: a high-quality ligand is known. PROTAC: UniProt records ubiquitination sites on it; ubiquitination databases record sites on it; a small molecule that binds it is known.
Safety:
Unwanted effects reported when the protein is acted on. In parentheses: how it was acted on, where the effect was seen, and who reports it.
Diabetes Mellitus (source: ClinPGx)
diabetes (source: ClinPGx)
new-onset diabetes after transplantation (source: ClinPGx)
new-onset diabetes after transplantation (NODAT) (source: ClinPGx)
new-onset diabetes mellitus (NODM) (source: ClinPGx)
Gene: Protein-coding gene on chromosome 10 (112,950,205 to 113,167,678, forward strand). Ensembl gene ENSG00000148737.
Subcellular location: Nucleus, PML body; Nucleus
Subcellular location (Human Protein Atlas): Nucleoplasm; Cytosol; Nuclear bodies
Pathways (Reactome):
Signal Transduction: Binding of TCF/LEF:CTNNB1 to target gene promoters; Ca2+ pathway; Deactivation of the beta-catenin transactivating complex; Formation of the beta-catenin:TCF transactivating complex; Repression of WNT target genes
Developmental Biology: Formation of definitive endoderm; Regulation of MITF-M-dependent genes involved in cell cycle and proliferation
Gene expression (Transcription): RUNX3 regulates WNT signaling; Transcriptional Regulation by VENTX
Disease: Signaling by TCF7L2 mutants
Immune System: Regulation of PD-L1(CD274) transcription
Metabolism of proteins: Synthesis, secretion, and inactivation of Glucagon-like Peptide-1 (GLP-1)
Gene Ontology:
Molecular function: armadillo repeat domain binding; beta-catenin binding; DNA-binding transcription factor activity; DNA-binding transcription factor activity, RNA polymerase II-specific; DNA-binding transcription repressor activity, RNA polymerase II-specific; gamma-catenin binding; nuclear receptor binding; protein binding; protein kinase binding; RNA polymerase II cis-regulatory region sequence-specific DNA binding; RNA polymerase II-specific DNA-binding transcription factor binding; sequence-specific DNA binding; transcription cis-regulatory region binding; transcription corepressor binding; promoter-specific chromatin binding
Biological process: blood vessel development; canonical Wnt signaling pathway; fat cell differentiation; glucose homeostasis; maintenance of DNA repeat elements; myoblast fate commitment; negative regulation of androgen receptor signaling pathway; negative regulation of canonical Wnt signaling pathway; negative regulation of DNA-templated transcription; negative regulation of transcription by RNA polymerase II; positive regulation of epithelial cell proliferation; positive regulation of epithelial to mesenchymal transition; positive regulation of heparan sulfate proteoglycan biosynthetic process; positive regulation of insulin secretion; positive regulation of phosphatidylinositol 3-kinase/protein kinase B signal transduction; positive regulation of protein localization to nucleus; positive regulation of transcription by RNA polymerase II; regulation of hormone metabolic process; regulation of smooth muscle cell proliferation; regulation of transcription by RNA polymerase II; negative regulation of extrinsic apoptotic signaling pathway; negative regulation of type B pancreatic cell apoptotic process; pancreas development; regulation of gluconeogenesis; response to glucose; and 2 more
Cellular component: beta-catenin-TCF7L2 complex; chromatin; nuclear body; nucleoplasm; nucleus; protein-DNA complex; beta-catenin-TCF complex; catenin-TCF7L2 complex; PML body
Genetic constraint (gnomAD): Loss-of-function variants: 23 observed, 68.77 expected, observed/expected ratio (o/e) 0.33, 90% interval 0.24 to 0.47. The synonymous counts are far from expectation, so gnomAD's model fits this gene poorly and the ratio says little. Missense variants: 654 observed, 760.93 expected, observed/expected ratio (o/e) 0.86, 90% interval 0.81 to 0.92. Synonymous variants: 413 observed, 329.31 expected, observed/expected ratio (o/e) 1.25, 90% interval 1.16 to 1.36.
Gene-disease validity (ClinGen):
ClinGen rates the evidence that TCF7L2 causes each of these diseases.
complex neurodevelopmental disorder (autosomal dominant): Definitive. A disorder that involves more than one phenotype associated with the central nervous system, including but not limited to intellectual disability, autism, and seizures (epilepsy).
Cancer hallmarks: proliferative signalling (promotes); invasion and metastasis (promotes); escaping programmed cell death (promotes)
Homologues: Orthologues: chimpanzee TCF7L2 (100% identical), mouse Tcf7l2 (95% identical), rat Tcf7l2 (94% identical), dog TCF7L2 (94% identical), pig TCF7L2 (94% identical), macaque TCF7L2 (92% identical), rabbit TCF7L2 (86% identical), tropical clawed frog tcf7l2 (86% identical), zebrafish tcf7l2 (72% identical), guinea pig TCF7L2 (55% identical). Paralogues in human: TCF7L1 (58% identical), LEF1 (41% identical), TCF7 (31% identical).
Diseases named in the same sentence as TCF7L2 in open-access papers:
TCF7L2 is named in the same sentence as 205 diseases in open-access papers, as found by Europe PMC text mining. Sharing a sentence is not in itself a finding about the gene and the disease. The quoted sentences say what the papers report.
type 2 diabetes (336 papers, 2006 to 2026). "The TCF7L2 locus is one of the strongest signals for type 2 diabetes and is associated with latent autoimmune diabetes in adults (LADA)." (PMID 40116328, 2025). "A significant association was also identified between TCF7L2 gene polymorphisms and type 2 diabetes mellitus (p for trend < 0.039)." (PMID 40303486, 2025). "Rs7903146, situated within the fourth intron of the TCF7L2 gene, is the only variant that captures the association with type 2 diabetes across different ethnic groups." (PMID 40116328, 2025). "The interacting SNP at TCF7L2, rs7903146, is the most strongly associated type 2 diabetes risk variant in the GWAS Catalog." (PMID 41332835, 2025). "Among the patients phenotyped for these biomarkers, we identified 54,649 individuals with the CC genotype, 44,178 with the CT genotype, and 9,192 with the TT genotype for the rs7903146 variant in TCF7L2, the strongest GWAS signal for type 2 diabetes." (PMID 40675550, 2025). "Transcription factor 7-like 2 (TCF7L2) is the first genetic locus with common variants that were identified by genome-wide association studies to associate with type 2 diabetes (T2D)." (PMID 40050721, 2025). "TCF7L2 gene had a strong association with diabetes traits, with P values ranging from 2.26 × 10−10 to 1.49 × 10−154, including diabetes and type 2 diabetes." (PMID 39471050, 2025). "At chromosome 10q25, the transcription factor 7-like 2 (TCF7L2) type 2 diabetes risk gene controls beta-cell function as well as insulin secretion." (PMID 40225541, 2025). "In 2006, TCF7L2 gene polymorphisms were identified in the Icelandic population in a binding region of chromosome 10 that were strongly associated with the risk of type 2 diabetes." (PMID 38384655, 2024). "A meta-analysis of genetic associations observed in different populations revealed that TCF7L2 variants linked with type 2 diabetes operate through a multiplicative genetic model." (PMID 38694942, 2024). "For example, the rs7903146 variant of the Transcription Factor 7 Like 2 (TCF7L2) gene was identified as associated with type 2 diabetes, and the T allele of this variant strongly predicts future type 2 diabetes." (PMID 38732608, 2024). "An interesting finding regarding genetic variation and fiber intake relates to the SNP rs7903146 TCF7L2 (transcription factor 7 like 2), which is known to yield the highest risk of type 2 diabetes (T2D) in Caucasians to date." (PMID 38281958, 2024). "While implicated in blood glucose regulation with variants linked to type 2 diabetes risk, TCF7L2’s primary function lies within the intestine." (PMID 39435285, 2024). "Specifically, variants at TCF7L2 were found to have the strongest association with type II diabetes in human GWAS." (PMID 37909330, 2023). "In vitro, TNF-α has been shown to increase the transcriptional activity of TCF7L2 (a gene that has consistently been associated with type 2 diabetes) leading to reduced adipogenesis." (PMID 37215099, 2023). "TCF7L2: Variants in the Transcription Factor 7-Like 2 (TCF7L2) gene represent the most significant genetic risk factor for type 2 diabetes, as evidenced by a meta-analysis involving over 30,000 individuals." (PMID 37965396, 2023). "We studied nPOD donors with type 1 diabetes and demonstrated a significant positive association between residual ICI%≥5 and the type 2 diabetes-associated TCF7L2 rs7903146 T allele (i.e. CT or TT genotype)." (PMID 36282337, 2023). "TCF7L2 is among the leading signals for type 2 diabetes risk and persists as a top signal after adjustment for BMI." (PMID 37433298, 2023). "The transcription factor 7-like 2 (TCF7L2) is the most potent locus for type 2 diabetes; as the association of TCF7L2 with type 2 diabetes has been consistently replicated in multiple populations with diverse genetic origins." (PMID 37215099, 2023). "Many studies have shown that alterations in Tcf7l2 expression are metabolically associated with type 2 diabetes." (PMID 36759348, 2023).
type 2 diabetes (continued). "According to genome-wide association studies in humans, Tcf7l2 is one of the strongest risk factors associated with type 2 diabetes." (PMID 36759348, 2023). "The type 2 diabetes-associated TCF7L2 variant was found in homozygosis (TT genotype) or heterozygosis (TC genotype) or was absent (CC genotype) in 3.6%, 41.8% and 54.5% of the 110 donors, respectively." (PMID 36282337, 2023). "The SNP rs7903146 of the TCF7L2 gene is the most significant genetic marker associated with type 2 diabetes risk in all the ethnicities." (PMID 37192883, 2022). "Potapov V.A., Nosikov V.V., Shamkhalova M.N., Shestakova M.V., SmetaninaS.A., Bel’chikova L.N., Suplotova L.A. TCF7L2 rs12255372and SLC30A8 rs13266634 confer susceptibility to type 2 diabetes ina Russian population." (PMID 35434484, 2022). "Transcription factor 7-like 2 (TCF7L2) gene rs7903146 polymorphism is a common type 2 diabetes-associated variant." (PMID 35585604, 2022). "The gene of transcription factor 7-like 2 (TCF7L2) is the locus most associated with type 2 diabetes." (PMID 36555645, 2022). "It has been shown that type 2 diabetes mellitus is strongly associated with gene variants of the Wnt signaling pathway, specifically polymorphisms of TCF7L2 (transcription factor 7 like 2), which is an effector transcription factor of this pathway." (PMID 35436882, 2022). "For example, in the Diabetes Prevention Program and Diabetes Prevention Study, participants with the risk genotype TT in the TCF7L2 rs12255372 showed lower type 2 diabetes incidence in the intervention group than in the control group." (PMID 35501401, 2022). "A common intronic variant in TCF7L2, rs7903146, is a well-known causal risk allele for type 2 diabetes." (PMID 36040971, 2022). "The subjects were originally recruited based on their genotype at rs7903146 in the TCF7L2 locus where the T (the type 2 diabetes‐associated) allele increased disorderliness of insulin secretion and impaired postprandial suppression of glucagon." (PMID 35822422, 2022). "In 1999, variants in the TCF7L2 gene were initially associated with colon cancer (CC), and in 2006 with type 2 diabetes mellitus (T2D)." (PMID 34612510, 2022). "Cauchi S., El Achhab Y., Choquet H., Dina C., Krempler F., WeitgasserR., Nejjari C., Patsch W., Chikri M., Meyre D., Froguel P.TCF7L2 is reproducibly associated with type 2 diabetes in variousethnic groups: a global meta-analysis." (PMID 35434484, 2022). "Katsoulis K., Paschou S.A., Hatzi E., Tigas S., Georgiou I., Tsatsoulis A.TCF7L2 gene variants predispose to the development of type 2diabetes mellitus among individuals with metabolic syndrome.Hormones(Athens)." (PMID 35434484, 2022). "Both the TCF7L2 SNP rs7903146, which is known for its association with type 2 diabetes, and a genetic score for type 2 diabetes were associated with SIDD, MOD and MARD but not with SIRD." (PMID 34981134, 2022). "An initial gene-candidate study highlighted that the TCF7L2 (Transcription factor 7-like 2) gene, known to be associated with type 2 diabetes in the general population, was also associated with CFRD." (PMID 36430680, 2022). "GWAS has also linked genetic variations in TCF7L2, a key component of canonical Wnt pathway, to type 2 diabetes in humans." (PMID 35503096, 2022). "Later, the TCF7L2 gene was linked to type 2 diabetes (T2D), implicating TCF7L2 and Wnt‐signaling in metabolic disorders and homeostasis." (PMID 34612510, 2022). "It is reported that single-nucleotide polymorphism(SNP) in human TCF7L2 genes has a close relationship with occurrences of type 2 diabetes after extensive genome studies in numerous ethnic populations." (PMID 35677638, 2022). "Impairment of hepatic insulin sensitivity and induction of insulin resistance are among molecular mechanisms through which TCF7L2 rs7903146 variant increases the risk of type 2 diabetes and its most common comorbidity." (PMID 35585604, 2022).
type 2 diabetes (continued). "The gene encoding transcription factor 7-like 2 (TCF7L2), which is known to affect pancreatic secretory function, has also been described in African populations with type 2 diabetes." (PMID 35138411, 2022). "Loss of function mutations in TCF7L2 have been associated to both prostate and colon cancer susceptibility and to an increased risk of Type II diabetes." (PMID 33821390, 2021). "On the contrary, some of the existing evidence has suggested the protective effects of dietary compounds, such as dietary fiber and cereals, on type 2 diabetes risk among individuals with C homozygote genotype of the TCF7L2." (PMID 33436000, 2021). "Genome-wide association studies have revealed a strong association with SNPs close to the TCF7L2 locus and the risk of developing of type 2 diabetes." (PMID 34568323, 2021). "Transcription factor 7-like 2 (TCF7L2) is a downstream effector of the Wnt/β-catenin signalling pathway implicated in type 2 diabetes risk through genome-wide association studies." (PMID 33068125, 2021). "The effect of TCF7L2 variants on risk of type 2 diabetes and obesity as well as modulation effect of BMI on the association between diabetes and TCF7L2 variants, have been controversial." (PMID 33436000, 2021). "The genetic risk factor most strongly associated with type 2 diabetes is TCF7L2 single nucleotide polymorphisms (SNPs)." (PMID 33828529, 2021). "Such patients often carry the type 2 diabetes-associated TCF7L2 gene variant and are more often overweight compared with patients with a more severe autoimmune reaction, i.e. multiple autoantibodies." (PMID 33331974, 2021). "Among different single nucleotide polymorphisms (SNPs), the transcription factor-7-like 2 (TCF7L2) rs7903146 and rs12255372 are assumed to be associated with type 2 diabetes as well as MetS in different populations." (PMID 33436000, 2021). "Transcription factor-7–like 2 (TCF7L2) is one of the most important susceptibility genes for type 2 diabetes mellitus (T2DM)." (PMID 34200102, 2021). "Two of these SNPs (rs4132670 and rs12255372) are intronic variants in TCF7L2 and have both been previously identified for association with type 2 diabetes as well as body mass index and retinopathy." (PMID 34086673, 2021). "Genetic variants in the transcription factor 7-like 2 (TCF7L2) gene are related with type 2 diabetes (T2D) and gestational diabetes mellitus (GDM) in various populations, but there are not enough statistics regarding GDM among Egyptian women." (PMID 34724590, 2021). "In genome-wide association studies (GWAS), the transcription factor-7 like 2 gene (TCF7L2) was the first locus associated to type 2 diabetes." (PMID 34202120, 2021). "A single-nucleotide substitution of TCF7L2, rs7903146, is a genetic high-risk factor for type 2 diabetes and indicates susceptibility to cardiovascular disease as a link between metabolic disorders and atherosclerosis." (PMID 34568447, 2021). "It has been observed and reported in several studies that due to polymorphism in TCF7L2, the risk of developing type 2 diabetes significantly increases." (PMID 34674647, 2021). "The non-autoimmune severe insulin-deficient diabetes cluster showed an association with a variant of the TCF7L2 gene, a locus which shows one of the strongest genetic associations with type 2 diabetes risk." (PMID 33594477, 2021). "Previous epidemiological studies have indicated that the TCF7L2 gene single nucleotide polymorphisms (SNPs) were associated with common diseases, including type 2 diabetes mellitus (T2DM) and DN." (PMID 34193317, 2021). "SNP rs6585206, that we used as the IV, was located in TCF7L2 gene, which has been reported to be associated with schizophrennia and type 2 diabetes." (PMID 34628468, 2021). "Studies on various ethnic populations have confirmed that TCF7L2 SNPs are strongly associated with Type 2 diabetes (T2DM) risk." (PMID 35664972, 2021).